B4GALNT1 (beta-1,4-N-acetyl-galactosaminyltransferase 1)
Description:
Involved in the biosynthesis of gangliosides GM2, GD2, GT2 and GA2 from GM3, GD3, GT3 and GA3, respectively.
Synonyms: GALGT; beta1-4GalNAc-T; GALNACT; GalNAc-T; SPG26
Tractability: Antibody: UniProt predicts a signal peptide or a membrane-spanning region. PROTAC: ubiquitination databases record sites on it; its protein half-life has been measured.
Gene: Protein-coding gene on chromosome 12 (57,623,409 to 57,633,239, reverse strand). Ensembl gene ENSG00000135454.
Subcellular location: Golgi apparatus membrane
Pathways (Reactome):
Metabolism: Glycosphingolipid biosynthesis
Gene Ontology:
Molecular function: (N-acetylneuraminyl)-galactosylglucosylceramide N-acetylgalactosaminyltransferase activity; acetylgalactosaminyltransferase activity; hexosyltransferase activity
Biological process: ganglioside biosynthetic process; carbohydrate metabolic process; glycosphingolipid metabolic process; carbohydrate derivative metabolic process
Cellular component: Golgi apparatus; Golgi membrane; membrane
Genetic constraint (gnomAD): Loss-of-function variants: 43 observed, 49.76 expected, observed/expected ratio (o/e) 0.86, 90% interval 0.68 to 1.11. The upper end of that interval is the gene's LOEUF score, 1.11, which puts it in group 4 of 6, group 1 being the genes least tolerant of losing a copy. Missense variants: 664 observed, 691.5 expected, observed/expected ratio (o/e) 0.96, 90% interval 0.9 to 1.02. Synonymous variants: 305 observed, 292.84 expected, observed/expected ratio (o/e) 1.04, 90% interval 0.95 to 1.14.
Gene-disease validity (ClinGen):
ClinGen rates the evidence that B4GALNT1 causes each of these diseases.
complex hereditary spastic paraplegia (autosomal recessive): Definitive. A hereditary spastic paraplegia that is part of a larger syndrome.
Homologues: Orthologues: chimpanzee B4GALNT1 (99% identical), macaque B4GALNT1 (99% identical), rabbit B4GALNT1 (93% identical), dog B4GALNT1 (93% identical), pig B4GALNT1 (92% identical), guinea pig B4GALNT1 (91% identical), rat B4galnt1 (88% identical), mouse B4galnt1 (87% identical), zebrafish b4galnt1b (55% identical), tropical clawed frog b4galnt1 (53% identical), zebrafish b4galnt1a (49% identical). Paralogues in human: B4GALNT2 (40% identical).
Diseases named in the same sentence as B4GALNT1 in open-access papers:
B4GALNT1 is named in the same sentence as 62 diseases in open-access papers, as found by Europe PMC text mining. Sharing a sentence is not in itself a finding about the gene and the disease. The quoted sentences say what the papers report.
hereditary spastic paraplegia (16 papers, 2018 to 2025). Hereditary spastic paraplegias (HSP) comprise a genetically and clinically heterogeneous group of neurodegenerative disorders characterized by progressive spasticity and hyperreflexia of the lower limbs. "The N2a B4galnt1 KO cells used in our study model the ganglioside biosynthetic defect resulting from mutations in the human B4GALNT1 gene, which causes a form of hereditary spastic paraplegia." (PMID 40961208, 2025). "Loss of B4GALNT1 function causes hereditary spastic paraplegia, while its overexpression is linked to cancers including childhood neuroblastoma." (PMID 40593514, 2025). "When the genetic mutation is found in B4GALNT1, this can be diagnosed as B4GALNT1‐associated hereditary spastic paraplegia (SPG26), while the responsible gene in the first case was found to be present on chromosome 12 in 2005." (PMID 36999634, 2023). "Congenital disruption of the same gene in humans, B4GALNT1, was found to be the cause of one form of hereditary spastic paraplegia, a syndrome with symptoms much like those of B4galnt1-null mice." (PMID 34065256, 2021). "A similar phenotype is shown by Mag-null mice and by patients with hereditary spastic paraplegia caused by mutations in the MAG or in the B4GALNT1 gene." (PMID 33117120, 2020). "B4GALNT1 mutations occur in subjects with hereditary spastic paraplegia (HSP), a group of inherited neurodegenerative disorders characterized by progressive spasticity and weakness of the legs." (PMID 32731387, 2020). "Loss of function of the GM2 synthase due to mutations in B4galnt1 results in hereditary spastic paraplegia." (PMID 31887977, 2019). "Mutations in B4GALNT1 (encoding GM2/GD2 synthase) lead to hereditary spastic paraplegia accompanied by intellectual disability." (PMID 31867330, 2019). "Hereditary spastic paraplegia is known to be associated with mutations in the B4galnt1 gene encoding GM2/GD2 synthase, a rate-limiting enzyme in the synthesis of the complex gangliosides abundant in central nervous system tissues." (PMID 31887977, 2019). "In fact, mutated B4galnt1 has been demonstrated in patients with hereditary spastic paraplegia." (PMID 34768952, 2021). "Recently, 11 cases of hereditary spastic paraplegia (HSP) due to mutation in the coding region of B4GALNT1 were reported." (PMID 32168753, 2020). "Mutations in B4GALNT1, which codes for GM2/GD2 synthase, are linked to a form of hereditary spastic paraplegia characterized by limb spasticity, dysarthria, peripheral neuropathy, and severe intellectual disability." (PMID 31447771, 2019). "Loss-of-function mutations in the B4GALNT1 gene cause a block of ganglioside biosynthesis downstream of GM3 and GD3 and increased GM3 levels, resulting in a complicated form of hereditary spastic paraplegia (HSP26)." (PMID 33117120, 2020). "In recent years, congenital mutations in the human B4GALNT1 gene encoding GM2/GD2 synthase have been associated with the human autosomal recessive disorder, hereditary spastic paraplegia (HSP)." (PMID 34948386, 2021).
melanoma (9 papers, 2019 to 2025). A malignant, usually aggressive tumor composed of atypical, neoplastic melanocytes. "Forced expression of B4GALNT1 in human melanoma cells increased GM2 levels as well as cleavage of amyloid precursor protein that is associated with the pathophysiology of Alzheimer’s disease (AD)." (PMID 40942141, 2025). "In this study, we analyzed a variety of changes in the SH4 melanoma cell line upon overexpression of GM2/GD2 by transfection of B4GALNT1 gene." (PMID 31988291, 2020). "In summary, our findings demonstrated that in the SH4 melanoma cell line, overexpression of B4GALNT1 as well as its main products GM2/GD2 promotes AIG and cell migration in vitro and enhances tumor incidence by inducing angiogenesis in vivo." (PMID 31988291, 2020). "We overexpressed B4GALNT1 in GM2/GD2-negative human melanoma cell line (SH4) and confirmed production of GM2/GD2 by HPLC." (PMID 31988291, 2020). "We previously demonstrated that expression levels of GD3 synthase (ST8SIA1) and GM2/GD2 synthase (B4GALNT1) genes were markedly high in melanoma lines compared with melanocytes." (PMID 31611597, 2019). "An inhibition of GM2 synthesis may thus be useful to study the role of GM2/GD2 in human tumor cells (malignant melanoma lines, neuroblastoma lines, and some glioma lines) that express high levels of B4GALNT1 mRNA." (PMID 40942141, 2025). "Increased expression of B4GALNT1 promotes metastasis of lung adenocarcinoma and melanoma." (PMID 34745942, 2021). "Consequently, the GD3 synthase gene (ST8SIA1) was highly expressed only in the melanoma cell lines examined, and GM2/GD2 synthase (B4GALNT1) was also expressed only in melanoma cells." (PMID 31611597, 2019). "Our findings indicate the involvement of B4GALNT1 and GM2/GD2 in tumor establishment and progression as well as a potential direction of therapeutic approach via controlling B4GALNT1, and consequently GM2/GD2 expression in cancers such as melanoma." (PMID 31988291, 2020). "B4GALNT1 is involved in the synthesis of GM2 and GD2, key melanoma cell surface glycosphingolipids, which is frequently found in advanced-stage melanomas and in patients showing more aggressive melanoma tumors, whereas normal donor PBMCs were negative for B4GALNT1 mRNA expression." (PMID 35205608, 2022). "That indicated that B4GALNT1 was unlikely to affect the stemness in the SH4 melanoma cell line." (PMID 31988291, 2020).
Parkinsonism (9 papers, 2013 to 2021). Characteristic neurologic anomaly resulting from degeneration of dopamine-generating cells in the substantia nigra, a region of the midbrain, characterized clinically by shaking, rigidity, slowness of movement and difficulty with walking and gait. "The initial observation of Parkinsonism in B4GALNT1 KO mice documented loss of neurons in substantia nigra, a loss that could be substantially ameliorated by dosing animals with the semi-synthetic, brain-permeable GM1 ganglioside analog, LIGA20." (PMID 29459819, 2018). "Also, B4galnt1 knockout mice and their heterozygotes manifest Parkinson’s disease (PD)-like symptoms along with the loss of dopaminergic neurons, and such abnormalities are attenuated by administration of LIGA20." (PMID 24961420, 2013). "Given the recent in vitro discovery that the free soluble oligosaccharide of GM1 is the bioactive portion of GM1 for neurotrophic functions, we investigated its therapeutic potential in the B4galnt1+/− mice, a model of sporadic Parkinson’s disease." (PMID 31852959, 2019). "We have also observed progressive Parkinsonism in B4GALNT1 heterozygotes that, although slower in onset that the homozygotes, is indistinguishable otherwise." (PMID 29459819, 2018). "Recent studies have reported that mice with knockout of the B4Galnt1 gene have loss of a-and b-series gangliosides including GM1, and develop a progressive parkinsonism." (PMID 29902255, 2018). "Interestingly, GM1 pentasaccharide was shown to provide beneficial effects similar to those exerted by GM1 in the B4galnt1+/– mouse model of parkinsonism." (PMID 33117120, 2020). "Thus, this study supports the idea that the Parkinson’s phenotype expressed by the B4galnt1+/− mice is due to a reduced level of neuronal ganglioside content and lack of interactions between the oligosaccharide portion of GM1 with specific membrane proteins." (PMID 31852959, 2019). "We hypothesized that the Parkinsonism, evinced by both homozygous and heterozygous B4GALNT1 mice, might be due to a GM1 ganglioside requirement by the GDNF receptor for efficient signaling." (PMID 29459819, 2018). "B4GALNT1 knockout mice, an enzyme upstream of GM1 production, develops parkinsonism." (PMID 34884663, 2021). "The total ablation of the B4galnt1 gene in mice (B4galnt1−/− mice), leads to the complete absence of gangliosides of the ganglio-series and increased GM3 and GD3, accompanied by a phenotype of severe neurodegeneration that recapitulates severe parkinsonism." (PMID 32013258, 2020).
neuroblastoma (7 papers, 2019 to 2025). Neuroblastoma (NB) is the most common solid, extracranial childhood tumor. "We next addressed if the trans-interaction between SLAMF7 on macrophages and neuroblastoma cells could occur by examining SLAMF7 expression on the tumor cells relative to those of B4GALNT1 (GD2 synthase gene) and ST8SIA1 (GD3 synthase gene) in high-risk neuroblastoma tissues." (PMID 35525858, 2022). "B4GALNT1 and ST8SIA1 are responsible for the expression of GD2, the well-recognized target of neuroblastoma immunotherapy." (PMID 35525858, 2022). "Finally, neuroblastoma and leukemia samples were compared, the 2-gene signature had an MCC value slightly lower than B4GALNT1 (0.98 and 1, respectively) but higher than the other genes." (PMID 32486168, 2020). "qPCR-based MRD detection by B4GALNT1 or TH mRNAs in PBSC samples did not affect survival of stage 4 neuroblastoma patients." (PMID 31214500, 2019). "GD2 positivity in bone marrow cells may represent a useful prognostic marker for patients with non-metastatic neuroblastoma, and B4GALNT1 has been suggested to be a pan-cancer biomarker." (PMID 40942141, 2025).
breast carcinoma (6 papers, 2018 to 2025). "Ganglioside GD2 was also identified as a putative marker of CD44hiCD24lo breast cancer stem cells (CSC) capable of initiating tumors, and several GT genes involved in GD2 biosynthesis (ST3GAL5, B4GALNT1, and ST8SIA1) are highly expressed in CSC." (PMID 29698439, 2018). "We evaluated gene expression data in TNBC and non-TNBC breast cancer samples using the TCGA dataset and observed higher expressions of ST8SIA1 and B4GALNT1 genes, and a higher score of the 2-gene signature in TNBC." (PMID 32486168, 2020).
cerebellar ataxia (4 papers, 2017 to 2024). A neurological syndrome characterized by clumsy and uncoordinated movement of the limbs, trunk, and cranial muscles. "Mutations in B4GALNT1 were also reported to in relation to autism spectrum disorder as well as cerebellar ataxia." (PMID 33638609, 2021). "For example, pathogenic variants in the ceramide synthase gene CERS2 cause epilepsy and ataxia, and mutations in genes involved in sphingolipid metabolism such as B4GALNT1, GBA2, and even FA2H, cause different forms of spasticity and ataxia, such as SPG26, SPG46, and SPG35, respectively." (PMID 38911600, 2024). "Mutations in beta-1,4-N-acetyl-galactosaminyl transferase 1 (B4GALNT1; GM2 synthase) result in early-onset HSP, intellectual disability, cerebellar ataxia, peripheral neuropathy and cortical atrophy." (PMID 29163032, 2017).
Intellectual disability (4 papers, 2017 to 2020). "B4GALNT1 is mutated in SPG26 that is characterized by complex HSP frequently associated with intellectual disability." (PMID 32180696, 2020).
lung adenocarcinoma (4 papers, 2021 to 2026). A carcinoma that arises from the lung and is characterized by the presence of malignant glandular epithelial cells. "Various studies demonstrated that B4GALNT1 was involved in the progression of different cancer types including oral squamous cell carcinoma and lung adenocarcinoma." (PMID 36746917, 2023). "In vitro, within lung adenocarcinoma cell lines, B4GALNT1 knockdown and CERS4 overexpression suppressed cell proliferation, migration, and epithelial-to-mesenchymal transition, supporting their roles in lung adenocarcinoma progression." (PMID 41666167, 2026).
cervical cancer (2 papers, 2022). A primary or metastatic malignant neoplasm involving the cervix. "Compared with normal cervix tissues, the expressions of several glycosyltransferases in cervical cancer tissues were upregulated, including GALNT2, POGLUT1, EXT1, B3GAT3, B4GALNT1 and UGT8 (GSE9750)." (PMID 36110252, 2022).
endometrial carcinoma (2 papers, 2019 to 2021). A malignant tumor arising from the epithelium that lines the cavity of the uterine body. "Another study identified B4GALNT1 to be related to endometrial cancer." (PMID 31552087, 2019).
glioma (2 papers, 2021 to 2024). A benign or malignant brain and spinal cord tumor that arises from glial cells (astrocytes, oligodendrocytes, ependymal cells). "High levels of B4GALNT1 have been detected in adult leukemia cells, neuroblastoma cell lines, glioma cell lines, and some malignant melanoma cell lines." (PMID 39616302, 2024). "SPP1 was also reported to promote the infiltration of TAMs in glioma, which is similar to our results in B4GALNT1-overexpressing HCC cell lines." (PMID 39616302, 2024). "Six of those genes were found in three of the six most enriched ‘glioma TADs’: 2160 (CDK4, TSFM, TSPAN31, B4GALNT1), 2337 (NFATC4) and 2688 (CACNA1G)." (PMID 34341417, 2021).
hepatocellular carcinoma (2 papers, 2024 to 2025). A malignant tumor that arises from hepatocytes. "In this study, we aimed to investigate the roles of B4GALNT1 in hepatocellular carcinoma (HCC), particularly in reshaping the tumor immune microenvironment, and evaluate the potential beneficial effects of targeting B4GALNT1 in immunotherapy." (PMID 39616302, 2024).
hereditary spastic paraplegia 26 (2 papers, 2024 to 2025). A rare, complex type of hereditary spastic paraplegia characterized by the onset in childhood/adolescence (ages 2-19) of progressive spastic paraplegia associated mainly with mild to moderate cognitive impairment and developmental delay, cerebellar ataxia, dysarthria, and peripheral neuropathy. "GM2S deficiency was revealed when a mutation in the B4GALNT1 gene was identified as the cause of hereditary spastic paraplegia 26 (SPG26)." (PMID 39119456, 2024). "Notably, mutations in B4GALNT1 have been confirmed to cause hereditary spastic paraplegia type 26 (HSP26), a neurodegenerative disorder characterized by progressive lower limb weakness and spasticity." (PMID 40870030, 2025).
lung carcinoma (2 papers, 2015 to 2022). "We selected 6 loci displaying significant differential cirDNA modification in the microarray analysis (Rab3a, Atp6v0c, B4galnt1, Slc1a1, Ttl and Krt15) and whose corresponding genes have been reported as associated to lung cancer phenotypes." (PMID 25415227, 2015).
osteosarcoma (2 papers, 2023 to 2025). A usually aggressive malignant bone-forming mesenchymal neoplasm, predominantly affecting adolescents and young adults. "Further, some gene targets already investigated in the ACT of osteosarcoma, including B4GALNT1 (encoding beta‐1,4‐N‐acetyl‐galactosaminyltransferase 1 involved in the biosynthesis of GD2), ERBB2, and EGFR, also showed low expression in osteosarcoma compared with adjacent normal tissues." (PMID 37457661, 2023).
ovarian carcinoma (2 papers, 2017 to 2021). A malignant neoplasm originating from the surface ovarian epithelium. "For example, alpha-2,8-sialytransferase 1 (ST8SIA1) and beta-1,4-N-acetyl-galactosaminyltransferase 1 (B4GALNT1), regulated by miR-33a and let-7e, increase expression of gangliosides (GD2 and GD3) in ovarian cancer." (PMID 34158025, 2021). "Interestingly, two of the four possible β1‐4‐acetylgalactosamine transferase genes (B4GALNT1‐4), B4GALNT3 and B4GALNT4, were found to be significantly elevated (P < 0.05) in the ovarian cancer tissues as compared to the peritoneum." (PMID 28853212, 2017).
renal carcinoma (2 papers, 2018 to 2022). A carcinoma arising from the epithelium of the renal parenchyma or the renal pelvis. "In renal carcinoma cells, TNF increased the expression of GM2 by enhancing the mRNA level of B4GALNT1 encoding the GM2/GD2 synthase, and resulted in T cell death and immune dysfunction." (PMID 29698439, 2018). "Other research has shown that transferrin (TF) and beta-1,4-N-acetyl-galactosaminyltransferase 1 (B4GALNT1) are highly expressed in patients with ccRCC, and B4GALNT1 may affect the occurrence and progression of renal cancer through the Hippo signaling pathway." (PMID 36483738, 2022).
sarcoma (2 papers, 2022 to 2025). A usually aggressive malignant neoplasm of the soft tissue or bone. "Further, we identified B4GALNT1 amplification as a potential biomarker in sarcoma." (PMID 41424948, 2025). "Lastly, B4GALNT1 amplification could represent a biomarker to identify GD2-positive sarcoma samples." (PMID 41424948, 2025).
bladder cancer (1 paper, 2021). "Then, we downloaded the published scRNA-seq data of 8 bladder cancer tissues to further explore the underlying mechanisms of B4GALNT1." (PMID 34771607, 2021). "However, when we overexpressed B4GALNT1 in bladder cancer cell lines, there were no observable phenotypic changes, implying that B4GALNT1 might facilitate MIBC progression by cooperating with stromal cells." (PMID 34771607, 2021).
brain cancer (1 paper, 2024). A primary or metastatic malignant neoplasm affecting the brain. "Moreover, we also identified other clinically relevant GRGs, as is the case of ST8SIA1 and B4GALNT1, which contribute to the synthesis of ganglioside GD2, in brain cancers." (PMID 38384845, 2024).
brain tumors (1 paper, 2025). "We found that genes responsible for GD2 synthesis (B4GALNT1 and ST8SIA1) and CD276, encoding B7-H3, were expressed at similar or lower levels in MB than in other brain tumors." (PMID 41159102, 2025).
colorectal cancer (1 paper, 2014). A primary or metastatic malignant neoplasm that affects the colon or rectum. "Increased mRNA expression of B4GALNT1 was observed after DAC treatment in colorectal cancer yet this is the first report describing the association of B4GALNT1 methylation with PCa progression." (PMID 25277202, 2014).